WTAP (WT1 associated protein)
Diseases named in the same sentence as WTAP in open-access papers (continued):
Sharing a sentence is not in itself a finding about the gene and the disease.
glioblastoma (22 papers, 2017 to 2025). The most malignant astrocytic tumor (WHO grade IV). "Upregulated WTAP contributes to a high ROS environment that promotes the malignant progression of glioblastoma cells." (PMID 40097417, 2025). "WTAP is a nuclear protein associated with cellular proliferation and apoptosis regulation of GBM cells with being overexpressed in glioblastoma multiforme (GBM)." (PMID 38072944, 2023). "Recently, WTAP was found to be overexpressed in glioblastoma; its ablation repressed the migration and invasion of the glioblastoma cells by regulating EGFR activity." (PMID 37854284, 2023). "Further studies revealed that WTAP overexpression promoted the proliferation, invasion, and migration of glioblastoma cells." (PMID 36139062, 2022). "Since WTAP was first discovered as a prognostic factor in glioblastoma, more and more research has focused on its oncogenic role in various types of malignant tumors." (PMID 35733918, 2022). "For example, WTAP is overexpressed in glioblastoma and regulates glioblastoma cell migration and invasion." (PMID 34794452, 2021). "WTAP is over-expressed in the glioblastoma stem cells, controlling the invasion of glioblastoma cells via regulating epidermal growth factor (EGF) signaling." (PMID 33664770, 2021). "WTAP, another member of m6A writer, enhances proliferation, migration, invasion, and tumorigenicity of glioblastoma cells in xenotransplantation by mediating the phosphorylation of epidermal growth factor receptor (EGFR) and AKT." (PMID 33658391, 2021). "WTAP has been reported as an oncogene in various cancers; for example, WTAP promotes metastasis of glioblastoma cells via EGF." (PMID 32709063, 2020). "In glioblastoma, WTAP was identified as an independent prognostic factor; moreover, high expression of WTAP predicts poor overall patient survival." (PMID 32552682, 2020). "For instance, WTAP is overexpressed in glioblastoma and regulates motility of glioblastoma cells by controlling the activity of EGFR." (PMID 30143009, 2018). "For instance, the m6A methylation/demethylation pathway regulated glioblastoma stem cell self‐renewal and tumorigenesis, and METTL3, METTL14, and Wilms Tumor 1‐Associating Protein (WTAP) were highly expressed in myeloid leukemia." (PMID 29921017, 2018). "Previous studies have demonstrated that WTAP is overexpressed in glioblastoma tissues and promotes cell migration and invasion." (PMID 28212562, 2017). "Furthermore, transcription factor CEBPD-mediated Wilms tumor 1-associated protein (WTAP) promotes the stemness, growth, migration and glycolysis of glioblastoma stem cell-like cells (GSCs) and reduces their tumorigenicity in vivo." (PMID 40357368, 2025). "WTAP was also highly expressed in the tissues of the following cancer types: colon adenocarcinoma, cholangiocarcinoma, glioblastoma multiforme, head and neck squamous cell carcinoma, lung squamous cell carcinoma, esophageal carcinoma, kidney renal clear cell carcinoma, and stomach adenocarcinoma." (PMID 35480109, 2022). "For example, WTAP was identified as a prognostic factor in glioblastoma and might be an oncogenic protein in acute myeloid leukemia." (PMID 36171885, 2022). "We have characterized a novel miR-29a/QKI-6/WTAP axis in GSCs, which may provide theoretical support for the treatment of glioblastoma with miR-29a agomirs." (PMID 28212562, 2017). "Overexpression of WTAP facilitates renal cell carcinoma by stabilizing CDK2 transcript, and WTAP promotes the invasiveness of glioblastoma through enhancing the activity of EGFR." (PMID 36855062, 2023). "In addition, elevated levels were observed for RBM15B, WTAP, FTO, YTHDF2, YTHDF3, IGF2BP2, and IGF2BP3 in glioblastoma samples compared with normal brain controls." (PMID 38398118, 2024). "In human, the functional role of ZC3H13 other than interacting with WTAP is poorly understood, although a recent report suggests that mutant ZC3H13 may facilitate glioblastoma progression." (PMID 35236848, 2022).
acute myeloid leukemia (16 papers, 2018 to 2025). Acute myeloid leukemia (AML) is a group of neoplasms arising from precursor cells committed to the myeloid cell-line differentiation. "For example, bone marrow mesenchymal stem cell-derived exosomal miR-425-5p inhibited the proliferation, apoptosis, invasion, and migration of acute myeloid leukemia cells by targeting Wilms tumor 1-associated protein (WTAP)." (PMID 40328736, 2025). "Increasing evidence shows that WTAP contributes to aggressive features in many tumors, including renal cell carcinoma, colorectal cancer, glioblastoma, and acute myeloid leukemia (AML)." (PMID 36420139, 2022). "WTAP dysregulation is related to different kinds of tumors, such as cholangiocarcinoma, renal cell carcinoma, colon cancer, and acute myeloid leukemia." (PMID 34634995, 2021). "Several studies have indicated that METTL3, METTL14, and WTAP are highly expressed in patients with acute myeloid leukemia (AML) and function as oncogenes." (PMID 40171845, 2025). "WTAP was overexpressed in acute myeloid leukemia (AML) patients, and its expression was related to a poor survival rate." (PMID 36207306, 2022). "The Wilms tumor 1 (WT1)-associated protein (WTAP) is upregulated in many tumors, including, acute myeloid leukemia (AML), where it plays an oncogenic role by interacting with different proteins involved in RNA processing and cell proliferation." (PMID 30038300, 2018). "In acute myeloid leukemia (AML), WTAP is similarly up-regulated by HIF-1α and stabilizes lysine demethylase 4B (KDM4B) mRNA via m6A modification, driving cancer cell proliferation and survival." (PMID 40102715, 2025). "High METTL3, WTAP, FTO, ALKBH5, and YTHDF2 expression has been observed in all subtypes of acute myelogenous leukaemia (AML), and high WTAP, ALKBH5 and IGF2BP1 expression are related to the poor prognosis of AML patients." (PMID 35518355, 2022). "A clinical study has shown that WTAP is an oncogene in acute myelogenous leukemia (AML) 29; however, the function of WTAP as m6A methyltransferase cofactor in AML is unknown." (PMID 35154467, 2022). "For example, the m6A methyltransferases METTL3/14 and WTAP could act as oncogenic factors by promoting the translation of several oncogenes including c-MYC, BCL2, PTEN, and mTOR in acute myeloid leukemia." (PMID 33584787, 2020).
renal cell carcinoma (16 papers, 2018 to 2025). "In renal cell carcinoma, keratinocytes, and psoriasis, WTAP regulates the G1/S transition and G2/M transition by stabilizing specific mRNAs." (PMID 36207306, 2022). "Further study has shown that METTL3, along with METTL4, METTL14, NCBP1, and WTAP, may interact to impact cell cycle, renal cell carcinoma, and pathways that are included in cancer and hence may influence CRC growth." (PMID 40177651, 2025). "Although roles and mechanisms of WTAP have been elucidated in several types of carcinoma, including colon carcinoma, cholangiocarcinoma, glioma, hepatocellular carcinoma, pancreatic carcinoma and renal cell carcinoma, they remain elusive in ovarian cancer." (PMID 32998774, 2020). "In renal cell carcinoma (RCC), WTAP regulates the m6A modification of long non coding RNA TEX41 to promote cancer cell proliferation and metastasis." (PMID 41256854, 2025). "Besides, WTAP promotes renal cell carcinoma proliferation by regulating CDK2 mRNA stability." (PMID 39744575, 2025). "In addition, WTAP could facilitate cell proliferation and invasion abilities of cholangiocarcinoma and renal cell carcinoma cells." (PMID 33937023, 2021). "In addition, an increasing evidence has confirmed that WTAP plays crucial ontogenetic roles in various cancers, including gastric cancer, acute myelogenous leukemia, cholangiocarcinoma, colorectal cancer, glioma, pancreatic cancer, and renal cell carcinoma." (PMID 33937023, 2021). "Moreover, WTAP may play an oncogenic role in renal cell carcinoma by binding to the CDK2 transcript and enhancing its stability." (PMID 32998774, 2020). "WTAP regulates CDK2 mRNA stability, which is related to the G1/S transition, in renal cell carcinoma (RCC) and keratinocytes." (PMID 36207306, 2022).
bladder cancer (15 papers, 2020 to 2025). "Wilms tumor 1-associated protein (WTAP), which has been revealed to be a prognostic marker of several cancers (e.g., nasopharyngeal carcinoma and bladder cancer), serves as the downstream target of miRNA-758-3p." (PMID 38540273, 2024). "Immunohistochemical staining showed that WTAP expression in bladder cancer was significantly higher than that in normal tissues, and high expression of WTAP indicated a poor prognosis." (PMID 36207306, 2022). "METTL14, YTHDC1, and WTAP may be protective factors for bladder cancer, the higher expressions were related to the longer overall survival of patients, while IGF2BP1-3, YTHDF1, LRPPRC, ALKBH5, and FTO were risk factors for bladder cancer." (PMID 37701836, 2023). "Recent studies have reported an overexpression of WTAP in bladder cancer and AML." (PMID 36733939, 2022). "WTAP is highly expressed in bladder cancer cells and overexpression of it indicates poor prognosis." (PMID 32787827, 2020). "In addition, studies in bladder cancer demonstrate that specific circRNAs can scaffold the WTAP/METTL3/METTL14 complex to remodel m6A on target mRNAs and thereby modulate chemosensitivity, highlighting the potential bidirectional interplay between circRNAs and the m6A machinery in cancer." (PMID 41323393, 2025). "To determine the relevance of the regulation of PIGT, WTAP and GLUT1 in patients, we performed IHC staining of PIGT, WTAP, and GLUT1 on the bladder cancer tissue microarrays and tumor tissues were separated into PIGT-high/low-group." (PMID 38169393, 2024). "In bladder cancer, it was found that m6A RNA methylation regulators could participate in the malignant progression of bladder cancer, and a risk signature with three selected m6A RNA methylation regulators (FTO, YTHDC1, and WTAP) could serve as a promising prognostic biomarker." (PMID 33628782, 2021). "We found that three genes were correlated with the prognosis of bladder cancer, namely YTHDC1, FTO, WTAP." (PMID 34521394, 2021). "P < 0.1 as the reference standard, we found that three genes were correlated with the prognosis of bladder cancer, namely YTHDC1, FTO, WTAP." (PMID 34521394, 2021). "Moreover, both the mRNA and protein levels of WTAP were upregulated in bladder cancer, offering a potential novel approach for the diagnosis and treatment of bladder cancer." (PMID 36207306, 2022). "Elevated CBLL1 and WTAP expression in PCa compared with non-malignant prostate cells is consistent with results observed in other cancer types where higher CBLL1 expression has been reported in HCC and NSCLC, with elevated WTAP expression found in bladder cancer and AML." (PMID 36733939, 2022).
gastric cancer (15 papers, 2019 to 2025). A primary or metastatic malignant neoplasm involving the stomach. "WTAP has been shown to be highly expressed in gastric cancer and is associated with a poor prognosis." (PMID 37522921, 2023). "The high expression of WTAP is significantly associated with poor prognosis in gastric cancer patients." (PMID 37325054, 2023). "WTAP was overexpressed in gastric cancer and is associated with poor prognosis, and accelerates glucose uptake and promotes lactate production in gastric cancer cells." (PMID 36139062, 2022). "Overexpression of WTAP resulted in poor survival of gastric cancer patients via modulation of tumor-associated lymphocyte infiltration." (PMID 36003776, 2022). "Overexpression of WTAP contributed to poor prognosis of gastric cancer by affecting tumor-associated T lymphocyte infiltration." (PMID 33748145, 2021). "Since upregulated WTAP expressions have been revealed to be significantly associated with immunosuppression in malignancies like human hepatocarcinoma and gastric cancer, we also examined the mRNA levels of mouse immunosuppressive cytokine IL-10 in our model." (PMID 34081626, 2021). "N6-methyladenosine (m6A) is the most common RNA modifier in eukaryotes, and Wilms tumor 1 associated protein (WTAP) is an m6A methyltransferase that can enhance the stability of HK2 mRNA, thus promoting glycolysis in gastric cancer cases." (PMID 36438836, 2022). "WTAP is present at a high level in the tumor tissues of patients with gastric cancer and is significantly related to the prognosis of patients." (PMID 33777035, 2021). "Finally, WTAP promoted multiple chemotherapy resistance and radiotherapy resistance in gastric cancer." (PMID 37272931, 2023). "Therefore, further research on WTAP is required to establish it as a target for the clinical treatment of gastric cancer." (PMID 37522921, 2023). "WTAP is anticipated to be a new target for the clinical therapy of gastric cancer." (PMID 37522921, 2023). "In gastric cancer, high expression of WTAP suppresses tumor immunity and affects prognosis." (PMID 33777035, 2021). "Recently, it was confirmed that WTAP, as another core component of the methyltransferase complex, is highly expressed in gastric cancer (GC) and is markedly correlated with T-cell infiltration in GC238." (PMID 37217462, 2023). "Wilms tumor 1 associated protein (WTAP) is a key RNA N6-methyladenosine (m6A) methylase, which is involved in gastric cancer (GC) development, but its pathogenic mechanism is not clear." (PMID 39991580, 2025). "Mechanistically, WTAP promotes the stability of hexokinase 2 (HK2) mRNA, a core molecule that regulates glucose metabolism, thus increasing glucose uptake in gastric cancer cells." (PMID 36139062, 2022). "The detection of mRNA levels of m6A-modified enzymes (METTL3, WTAP, METTL14, VIRMA, RBM15, FTO, and ALKBH5) in gastric cancer tissues and adjacent tissues showed that the mRNA level of METTL3 was significantly higher in gastric cancer tissues." (PMID 34394353, 2021).
Obesity (14 papers, 2018 to 2025). Accumulation of substantial excess body fat. "Participating in this mechanism are “writer” methyltransferases, such as methyltransferase-like 3 (METTL3) and Wilms tumor 1-associated protein (WTAP), and “eraser” demethylases, such as AlkB homolog H5 (ALKBH5) and fat mass and obesity (FTO)." (PMID 40284466, 2025). "As a regulatory component of the m6A-methyltransferase machine, WTAP functions as a recruiter to drive the METTL3-METTL14 complex to its mRNA or lncRNA targets, and knockdown of WTAP has been shown to protect from diet-induced obesity, leading to improved insulin sensitivity." (PMID 39054531, 2024). "Many disease processes such as NASH, obesity, and diabetes have been found to be regulated by m6A RNA writer proteins such as methyltransferase like 3 (METTL3) and Wilm’s tumor 1–associating protein (WTAP) by altering m6A RNA modification or chromatin accessibility." (PMID 37777158, 2023). "In adipose tissue we observed that several m6A regulators (WTAP, VIRMA, YTHDC1 and ALKBH5) correlate with obesity and clinical variables." (PMID 34950106, 2021). "Although many more investigations are needed, our data collectively suggest that intervention of WTAP, METTL3, METTL14, or an undetermined target of cell cycle-related molecules is a strategy for preventing and treating obesity or obesity-related diseases." (PMID 29866655, 2018).
cholangiocarcinoma (13 papers, 2017 to 2024). A carcinoma that arises from the intrahepatic biliary tree (intrahepatic cholangiocarcinoma) or from the junction, or adjacent to the junction, of the right and left hepatic ducts (hilar cholangiocarcinoma). "The WTAP deficiency has been shown to inhibit cell migration, invasion, and tumorigenicity of cholangiocarcinoma (CCA)." (PMID 39457524, 2024). "Immunohistochemistry showed that WTAP was overexpressed in cholangiocarcinoma tissues and promoted the proliferation, invasion, and migration of cholangiocarcinoma cells." (PMID 36139062, 2022). "The overexpression of WTAP can significantly increase the metastasis and invasion of cholangiocarcinoma cells." (PMID 33029866, 2020). "WTAP is highly expressed in cholangiocarcinoma, especially in cholangiocarcinoma cells with metastasis to lymph nodes or vessels." (PMID 33029866, 2020). "WTAP was overexpressed in cholangiocarcinoma, especially in metastatic cholangiocarcinoma cells inside lymph nodes or vessels." (PMID 30039919, 2018). "For example, WTAP expedite cell migration and invasion in cholangiocarcinoma." (PMID 32787827, 2020). "In addition, WTAP overexpression in cholangiocarcinoma induced the expression of metastasis-related genes such as cathepsin H, matrix metallopeptidase 7 (MMP7), matrix metallopeptidase 28 (MMP28), and mucin 1 (Muc1); however, the specific regulatory mechanisms have not been investigated." (PMID 36139062, 2022). "In cholangiocarcinoma, high WTAP expression has been reported to significantly correlate with its TNM staging, and further in vitro experiments have shown that high WTAP expression can significantly promote the migration and invasion of cholangiocarcinoma cells." (PMID 35733918, 2022).
liver cancer (13 papers, 2020 to 2025). An epithelial or non-epithelial malignant neoplasm that arises from the liver. "CircCCAR1 can act as a molecular sponge of miR-127-5p targeting Wilms’ tumor 1-associating protein (WTAP) molecules to promote liver cancer cell growth and metastasis." (PMID 40109856, 2025). "Our previous study showed high expression level of WTAP was associated with increased incidence of liver cancer and adverse prognosis." (PMID 36171885, 2022). "The GEPIA online database was used to analyze the expression pattern of WTAP in liver cancer and normal tissues, as well as its correlation with the overall survival rate and clinical stage of liver cancer patients." (PMID 40568348, 2025). "Through complex m6A regulation, WTAP plays a critical role in tumor microenvironment remodeling, resistance development, and immune evasion in liver cancer." (PMID 39911396, 2025). "While immune checkpoint molecules are expressed at higher levels and anti-tumor immune cell infiltration is decreased, CD8+ T cell-mediated cytotoxicity against tumor cells is considerably reduced in liver cancer patients with elevated WTAP expression." (PMID 39911396, 2025). "Specifically, WTAP was upregulated in various types of cancer, such as liver cancer, esophageal cancer, AML, and osteosarcoma." (PMID 37297015, 2023). "The expression of WTAP in liver cancer tissues is significantly higher than that in the adjacent tissues." (PMID 33937023, 2021). "Furthermore, WTAP contributes significantly to the development of liver cancer immunotherapy resistance." (PMID 39911396, 2025). "Analogous to METTL14, WTAP upregulation in HCC promoted liver cancer development." (PMID 35806168, 2022). "Furthermore, WTAP plays a key role in liver cancer resistance to immunotherapy." (PMID 39911396, 2025). "In vitro experiments have found that downregulation of WTAP promoted the conversion of LC3-I to LC3-II (indicating autophagy formation), and inhibited the proliferation and metastasis of liver cancer cells by promoting autophagy." (PMID 37297015, 2023). "WTAP is significantly upregulated in HCC and promotes liver cancer development." (PMID 39744575, 2025). "Moreover, no prominent difference was observed in WTAP expression among liver cancer specimens of different stages." (PMID 40568348, 2025).